BRCA1 (BRCA1 DNA repair associated)
Diseases named in the same sentence as BRCA1 in open-access papers (continued):
Sharing a sentence is not in itself a finding about the gene and the disease.
breast cancer (continued). "Sanger sequencing of the coding sequences and exon–intron junctions of BRCA1 and BRCA2 on DNA from the blood samples of the patients who donated their breast cancer tissue for PDTX, had confirmed the absence of pathogenic germline mutations in both PDTX models." (PMID 40764992, 2025). "Noteworthy, when assessing BRCA1 epimutations in non-TNBC breast cancers, BRCA1 hypermethylation was frequently observed in the small group of so-called ER-low tumors (tumors revealing ER immunostaining between 1% and 10%), which has been shown to have gene expression signatures mirroring TNBC." (PMID 40225940, 2024). "In the absence of BRCA1/2 germline mutations, alterations in other specific homologous recombination (HR) genes, such as PALB2, CHEK2, ATM, and NBN, can lead to an increased risk of breast cancer development." (PMID 39272660, 2024). "It was found that FLNA was overexpressed in breast cancer cells compared to normal breast tissue and the absence of FLNA could impede the formation of BRCA1 foci following DNA damage to promote breast cancer progression." (PMID 39126025, 2024). "BRCA PVs are known to be correlated with younger age at diagnosis of breast cancer- median 38 years in BRCA1 mutation and 41 years in BRCA2 mutation, as compared to 43 years in non-BRCA mutated women, and for BRCA1- a higher incidence of high-grade tumors (87%) and triple-negative disease (73%)." (PMID 38365640, 2024). "The risk of developing breast cancer is increased by 7% to 8% in males with the BRCA2 mutation, compared to a 1% risk for males with BRCA1.6,7 BRCA2 mutations are the most common in male breast cancer; however, this mutation is not the only mutation that is tested for." (PMID 38912178, 2024). "We generated and characterized a transgenic mouse model (K14-Cre;Brca1fl/fl;Wwoxfl/fl) and observed that mice lacking both WWOX and BRCA1 developed basal-like mammary tumors and exhibited a decrease in 53BP1 foci and an increase in RAD51 foci, suggesting impaired DSB repair." (PMID 38499540, 2024). "Overall, while in breast cancer, hypoxia might exert a complex set of opposing interactions on VEGF, these findings demonstrate that hypoxia can epigenetically silence the key tumour suppressor BRCA1/2 increasing genomic instability with tumours." (PMID 39282472, 2024). "Our study echoes this trend, as evidenced by our findings on DFS and OS rates among groups categorized by PVs in associated genes (i.e., BRCA1, BRCA2, and HR-DDR or inherited breast cancer cases) and those with PVs in non-associated genes (i.e., other breast cancer cases)." (PMID 38893140, 2024). "In conclusion MBD2 protein interact to the BRCA1 gene promoter, and resveratrol modulates MBD2 gene expression, which in turn regulates BRCA1 gene expression, and inhibits cell proliferation, migration, and induces apoptosis in ER+, PR+ & Triple negative breast cancer cells." (PMID 38711004, 2024). "Thus, most BRCA1-related tumors fall within the category of “triple-negative” breast cancer (68%), overlapping with basal-like breast cancers." (PMID 38892081, 2024). "In sporadically occurring breast cancer, mesenchymal cells have been shown to promote EMT, but this enhancement of EMT by mesenchymal stromal cells has been shown to be upregulated by BRCA1 PVs, thereby further increasing the metastatic potential of tumours carrying BRCA1 PVs." (PMID 39682099, 2024). "There is a negative correlation between MBD proteins & BRCA1 protein expression in MCF-7 & T-47D cells which indicate that MBD proteins negatively regulate the BRCA1 protein expression in ER+ & PR+ & Triple negative breast cancer cells." (PMID 38711004, 2024). "Additionally, novel therapeutic agents targeting frequently mutated genes like PIK3CA or BRCA1/2 have been developed and approved for treating patients with human epidermal growth factor 2 (HER2)‐negative breast cancer." (PMID 38895905, 2024).
breast cancer (continued). "Therefore, a lack of NF2 ubiquitination in BRCA1- and BARD1-deficient breast cancer cells contributes to tumor formation." (PMID 39796693, 2024). "BRCA1 carriers showed the highest PRSs for ER-negative BC with a hazard ratio of 1.29 (95% CI 1.25–1.33), reflecting that those at the 5th and 95th percentiles of the PRSER distribution have predicted breast cancer risks to 80 years of age of 59% and 83%, respectively." (PMID 38397209, 2024). "SERPINA3 is expressed at higher level in epithelial cells of BRCA1 and BRCA2 mutation carriers compared with non-carrier; this has previously been shown to confer invasiveness and epithelial-to-mesenchymal transition (EMT) phenotype to breast cancer cells." (PMID 38059556, 2024). "In addition to the BRCA1/2 germline mutation carriers, recent studies suggest the presence of another clinically distinct group of hereditary breast cancer patients who are BRCA1/2 negative (BRCAx)." (PMID 38254240, 2024). "Currently, there are no ongoing applications of BRCA‐1 or BRCA‐2 gene replacement in breast cancer." (PMID 38827026, 2024). "However, it is important to note that BRCA1/2 PV and sporadic breast cancers have a wide range of phenotypes which are not mutually exclusive." (PMID 39682099, 2024). "Reduced levels of miR-218 have been reported in breast cancer-derived tumor tissues with increased cisplatin resistance as well as in a cisplatin-resistant MCF7 breast cancer subline, which was explained by the regulation of the tumor suppressor BRCA1 by miR-218." (PMID 38256203, 2024). "BRCA1 mutations are predominantly associated with estrogen receptor-negative breast tumors, but BRCA2 mutations are not linked to any specific pathological subtype of breast cancer." (PMID 38255960, 2024). "Moreover, studies have shown texture to be able to distinguish BRCA1 and BRCA2 carriers from women of low risk of breast cancer, which is not the case for density." (PMID 39202310, 2024). "The aim of the study was to investigate whether the in silico prediction tools (PolyPhen-2, SIFT, Mutation Taster and PROVEAN) could predict the potential clinical impact and significance of BRCA1/2 CIP/VUS alterations, eventually impacting the clinical management of Breast Cancer subjects." (PMID 39062721, 2024). "Additionally, recent studies have revealed that breast cancer cells lacking BRCA1 and SMARCAL1 exhibit resistance to PARP inhibitors and cisplatin, which is accompanied by RF stabilization but does not result in HR restoration." (PMID 39318358, 2024). "PREDICT for estrogen receptor (ER)-negative breast cancer had modest discrimination for BRCA1 carrier patients overall (Gönen & Heller unbiased concordance 0.65 in CIMBA, 0.64 in BCAC), but it distinguished clearly the high-mortality group from lower risk categories." (PMID 37173335, 2023). "Similar results were described in women with or without breast cancer and BRCA1 or BRCA2 carriers." (PMID 37628558, 2023). "The risks for breast and ovarian cancers in female relatives of BRCA1 carriers were significantly higher than the risks in female relatives of non-carriers (breast cancer: RR = 4.29, 95% CI = 3.50-5.27; P < 0.001 and ovarian cancer: RR = 21.95, 95% = CI 13.73-35.07; P < 0.001)." (PMID 36861435, 2023). "In addition, some studies have found that the inhibitory effects of olaparib do not always depend on BRCA1/2 status in ovarian and breast cancers." (PMID 37069726, 2023). "Overall, we developed an innovative method to study linear splicing and backsplicing, described the repertoire of BRCA1 and BRCA2 circRNAs, including 15 novel ones, and showed for the first time that a disequilibrium between BRCA1 and BRCA2 circRNAs and mRNAs plays a role in breast cancer." (PMID 37046838, 2023). "Besides incidence, the histopathological features of the breast cancers that develop before and after RRSO may provide us with more insight into the effects of RRSO on breast cancer in BRCA1/2 GPV carriers." (PMID 37046756, 2023).
breast cancer (continued). "The discrimination of BOADICEA did not vary much by the clinical data of the proband other than showing some improvement for clinical conditions more strongly associated with PVs in BRCA1 than in the other genes, such as for ovarian cancer or ER and HER2 negative breast cancer." (PMID 37237042, 2023). "To determine if BRCA1/2 may facilitate HR-dependent lesion bypass of APOBEC-induced DNA damage in breast cancer, we assessed SBS13 mutations for replicative asymmetry associated with deamination of the lagging strand template in the absence of BRCA1 or BRCA2." (PMID 37532520, 2023). "Therefore, we aimed to assess and compare ultrasound image findings, including vascularity and elasticity, and pathologic features of BRCA1 and BRCA2 breast cancers in Japanese women based on the categories of the Japan Association of Breast and Thyroid Sonology (JABTS) guidelines." (PMID 36905492, 2023). "However, the role of circHIPK3-related genes in breast cancer carrying BRCA1/2 has not been fully elucidated." (PMID 37426414, 2023). "Two samples were from the luminal A subtype (BCB‐0114 and BCB‐0090), three luminal B (BCB‐0021, BCB‐0020 and BCB‐0139), including an inflammatory breast cancer sample (BCB‐0020), and two triple‐negative subtype (BCB‐0066 and BCB‐0112), including a BRCA1 mutated sample (BCB‐0066)." (PMID 37691350, 2023). "Finally, we again sought to evaluate the translation of these findings to models of olaparib resistance in other clinically relevant tumors, and thus tested the sensitivity of an olaparib-resistant breast cancer PDX (CTG-0869, BRCA1/2 hemizygously deleted) to PRT543." (PMID 37861290, 2023). "The lack of BRCA1 expression could therefore contribute to the hyperactivation of the AKT pathway observed in breast cancer." (PMID 37877351, 2023). "Women who were BRCA1/BRCA2 mutation carriers and were under 45 years of age and who received risk-reducing salpingo-oophorectomy and hormonal replacement treatment did not affect their breast cancer rates." (PMID 37384143, 2023). "For example, bilateral mastectomy rather than localised excision may be performed in a BRCA1-positive woman with newly diagnosed breast cancer." (PMID 35868849, 2022). "Interestingly, the index cases were negative for BRCA1 and BRCA2 mutations, highlighting that this mutation in familial predisposition to breast cancer is sufficient to cause the disease on its own." (PMID 35650591, 2022). "The P/LP-Vs found both in BRCA1/2 genes and non-BRCA genes may increase the risk of breast cancer and alter drug responses." (PMID 36140642, 2022). "Besides, seven genes including BRCA1, FN1, CCNE1, CCND1, CHEK1, BUB3, and CDC25A were identified as the hub nodes by the PPI network, and CCNE1 and CHEK1 were confirmed to be related with the prognostic survival of the patients with breast cancer." (PMID 35186236, 2022). "Practice guidelines do not advise that platinum agents should be used for most patients with early stage, HER2-negative breast cancer; thus, we were surprised to find twofold greater odds of platinum receipt by BRCA1/2 PV carriers vs noncarriers with HR-positive, HER2-negative disease." (PMID 35723570, 2022).
breast cancer (continued). "Given the propensity for triple‐negative breast cancer with BRCA1 mutations, as anticipated, most of the identified mutations were in BRCA2; therefore, the findings may be less applicable to BRCA1‐associated breast cancers." (PMID 35128817, 2022). "Pathogenic germline mutations in the BRCA1 and BRCA2 (BRCA1/2) genes contribute to hereditary breast and ovarian cancer in white/mestizo Colombian women, but there is virtually no genetic data on breast cancer in Colombians of African descent." (PMID 35641219, 2022). "Methods: 302 women with LBC and 1567 without breast cancer were tested for BRCA1/2 PGVs." (PMID 33763779, 2022). "However, the place of PARPi in patients with endocrine-receptor positive, HER2 negative (ER+/HER2-) breast cancer has been less clearly defined due to the lower relative frequency of BRCA1/2 PV (~5%) along with more effective lines of treatments available." (PMID 35158866, 2022). "Due to the lack of estrogen, progesterone, and HER2 receptors, and the inactivation of the BRCA1 gene, hormonal therapy, one of the most common treatments for breast cancer, is not available, worsening the prognosis of the disease compared to other types of breast cancers." (PMID 35601827, 2022). "On the other hand, although pioglitazone inhibits aromatase expression by inhibiting proinflammatory prostaglandin E2 signaling and upregulating tumor-suppressor gene BRCA1, it does not inhibit mammary tumor growth induced by N-methyl-N-nitrosourea in Sprague-Dawley rats fed a high-fat diet." (PMID 35585577, 2022). "Our findings support an important role for RAD6B in mitotic spindle dynamics and centrosome function as it is the major RAD6 homolog overexpressed in breast cancer cells and suggest that inhibition of RAD6B could be applied to increase PTX sensitivities of BRCA1 wild type and mutant TNBC cells." (PMID 36258187, 2022). "The family history was negative for other cases of breast cancer or ovarian cancer, but DNA-testing for the BRCA1 and BRCA2 genes was offered based on a high grade serous ovarian tumour meeting at least the 10% likelihood threshold defined by UK NICE guidelines." (PMID 36068545, 2022). "Studies have shown that BRCA1 P/LP variant positive patients present with high-grade disease, compared to BRCA2 P/LP variant positive patients and with sporadic/non-hereditary cases of breast cancer." (PMID 35710434, 2022). "However, patients with breast carcinomas that are defective in DNA repair by homologous recombination (HR) due to the lack of function of BRCA1, BRCA2, or other repair proteins in the HR pathway, do benefit from Pt-based chemotherapy." (PMID 36467895, 2022). "However, these treatment options are not commonly effective in the treatment of BRCA1/2 breast cancers, which are typically “triple negative” with regard to presence of these targetable receptors." (PMID 34070674, 2021). "Previous investigations among young breast cancer patients have found an underutilization of germline genetic testing, but have been limited by small sample size, lack of diversity, and examination of BRCA1/2 genes only." (PMID 31802423, 2021). "The possible role of BRCA1 was also suggested by another study, in which its expression was evaluated in 29 patients with breast cancer and 22 patients with EOC who developed BMs: 65.5% of breast cancer patients and 68.2% of EOC patients showed a BRCA1 protein loss." (PMID 34943916, 2021). "In addition, we also observed ART558 sensitivity in an ex vivo cultured tumour organoid derived from a BRCA1-mutant breast cancer, KCL014BCPO, but not in a BRCA1 wild type breast cancer organoid cultured under similar conditions." (PMID 34140467, 2021).
breast cancer (continued). "BRCA1 and BRCA2 mutations are not uncommon in breast cancer patients." (PMID 34290354, 2021). "Our larger study supports this finding and found significant differences in the prevalence of some breast cancer genes (BRCA1, MSH6, and MUTYH) between the two ethnic groups, suggesting that germline genetics may impact ethnic differences in breast cancer tumor characteristics and survival." (PMID 34857041, 2021). "Moreover, BRCA1 and ER-α modulate the expression and secretion of VEGF in breast cancer cells." (PMID 35008272, 2021). "Her mother had breast cancer at age 41 and a non-informative BRCA1 and BRCA2 study result." (PMID 34771502, 2021). "Majority of human BRCA1-related breast cancers are negative for ERα, PR and/ or ERBB2." (PMID 34815798, 2021). "Our findings are consistent with previous work in this setting and illustrate that, in contrast to pathogenic variants in BRCA1 and BRCA2 which are less prevalent in women diagnosed at older ages, the prevalence of pathogenic variants in other breast cancer genes is independent of age at diagnosis." (PMID 34887416, 2021). "USP9X has recently been suggested to stabilize the breast cancer protein-1 (BRCA1) required for DSB repair by homologous recombination through its DUB enzymatic activity, and which is required for resistance to the PARP inhibitor olaparib in HeLa and breast cancer cells." (PMID 34277417, 2021). "Risk-reducing salpingo-oophorectomy is associated with a 96% reduction in the risk of tubo-ovarian cancer; and may be associated with a reduction in breast cancer risk in the carriers of BRCA2, but not BRCA1, variants." (PMID 34771713, 2021). "Also, BRCA1 levels are reduced or absent in many sporadic breast cancers due to gene silencing by promoter methylation or downregulation of the gene by other tumor suppressors or oncogenes." (PMID 34142659, 2021). "However, no downstream mediator of BRCA1 in regulation of EMT in breast cancers has been identified." (PMID 34373738, 2021). "The CHEK2 variants included 2 patients with CHEK2 del5395, 1 patient with CHEK2 1100delc and 1 patient with CHEK 2 IVS2 + 1G > A. Additionally, one patient in the matched group of 3,884 healthy controls without breast cancer was found to harbor a variant in both CHEK2 and BRCA1." (PMID 33507482, 2021). "However, TNBCs involve a heterogeneous group of breast cancers, and many TNBC patients do not have BRCA1/2 mutations." (PMID 33628586, 2021). "Unlike in breast cancer, the link between BRCA1 and EMT has not been investigated in HGSOC." (PMID 34356119, 2021). "A tendency towards worse DFS in the BRCA1 cohort was observed for both patients with hormone receptor-positive (adjusted HR = 0.77, 95% CI 0.58–1.03) and negative (adjusted HR = 0.73, 95% CI 0.48–1.13) breast cancer (Pinteraction = 0.85)." (PMID 33579978, 2021). "In addition, mutations in BRCA1 are associated with the more aggressive, receptor-negative phenotype, whereas BRCA2 mutated breast cancers are predominantly hormone-sensitive." (PMID 34441794, 2021). "A further 397 papers (85.4%) were excluded after title and abstract evaluation, being non-English-language original reports, studies not regarding breast cancers, studies performed on animals, review papers, or studies not evaluating the BRCA1 gene methylation status." (PMID 33808555, 2021). "However, there were more HR+/HER2- breast cancers in BRCA2 mutation-carriers (57.0%) and fewer in BRCA1 mutation-carriers (22.6%) than the non-carriers (40.9%, p=1.4×10-5 and 3.0×10-4, respectively)." (PMID 34336698, 2021). "In terms of the first DFS event, second primary malignancies (breast cancer: 17.0% vs. 12.2%, P = 0.009; non-breast cancer: 4.3% vs. 1.9%, P = 0.02) were more frequent in the BRCA1 cohort while distant recurrences were less frequent (10.4% vs. 15.4%, P = 0.02) as compared to the BRCA2 cohort." (PMID 33579978, 2021).